CD4 (CD4 molecule)
Diseases named in the same sentence as CD4 in open-access papers (continued):
Sharing a sentence is not in itself a finding about the gene and the disease.
tumor (continued). "Unlike CD4+ Regulatory T cells (T6) presented in the early stage, PD‐1+ clusters were mainly present in the late stage, but neither of them show a significant difference between tumor and adjacent tissue." (PMID 39252823, 2024). "Tumor antigens are initially recognized and processed by antigen-presenting cells (APCs), such as dendritic cells, and subsequently presented on MHC class I and MHC class II molecules to CD8+ T cells and CD4+ T cells, respectively, collectively driving a robust antitumor immune response." (PMID 39877377, 2024). "However, interactions between macrophages and CD4+T cells are not always so beneficial for eliminating tumor cells." (PMID 38279145, 2024). "Furthermore, compared to IP-administered saline and free anti-PD-L1 mAb controls, anti-PD-L1-NP induced superior tumor regressions, and immunohistochemistry (IHC) on treated tumors revealed an increase in tumor-infiltrating CD8+ and CD4+ T cells only in the anti-PD-L1-NP group." (PMID 39339217, 2024). "We next investigated whether these tumours had an infiltration of T cells (CD103, CD4, CD3, and CD8) and B cells (CD20) or expressed immune checkpoints (PD-L1, TIGIT, and LAG3) as these features are known to positively correlate with a response to immunotherapy." (PMID 38672534, 2024). "The DERRDGs RiskScore was highly correlated with various CD4 T cells, most CD8 T cell, most helper cells, most B cells, various dendritic cells, natural killer cells, macrophages, eosinophils, mast cells, and monocytes, as assessed for enrichment of 28 immune infiltrating cells in tumor samples." (PMID 39507711, 2024). "Additionally, CD4+ and CD8+ T cells are often found at tumor margins." (PMID 39493764, 2024). "In addition, an analysis of the tumor microenvironment revealed a simultaneous reduction in CD3+CD8+ T-cell infiltration and inflation in the tumor-resident activity of CD4+FOXP3+ T-reg cells in SNORA38B OE conditions, while the exact opposite effect was observed in SNORA38B KO samples." (PMID 38474168, 2024). "CD4+ Helper T Cells (Th Cells): CD4+ T cells promote CTL proliferation and activation by secreting cytokines, enhance the antigen-presenting capability of DCs, and contribute to the formation of memory CTLs, thus playing a key role in long-term anti-tumor immunity." (PMID 39315102, 2024). "Interestingly, we observed that only the CD3+ T lymphocytes derived from zebularine-treated mice inhibited tumor growth, whereas adoptive therapy with CD4+ or CD8+ T cells alone did not delay tumor growth." (PMID 38755254, 2024). "IHC staining of PC3 tumor xenografts treated with anti-Siglec-7/9 mAbs demonstrated higher levels of apoptosis (cleaved caspase 3), decreased proliferation (Ki67), vascularization (CD31), and increased immune cell infiltrates, including CD4+ and CD8+ T cells compared with IgG controls." (PMID 39436703, 2024). "First, we confirmed that CD4+ T cells in transplanted B16-3340 tumors or the tumor-draining lymph node (TdLN) do not produce IL-17A, unlike cells from the small intestine, by using IL-17A-GFP reporter mice colonized with SFB and treated with anti-PD-1 antibody." (PMID 39185202, 2024). "Additionally, CD4+ and CD8+ T cells in the TD cluster demonstrated higher levels of exhaustion, suggesting decreased T- cell functionality and reduced efficacy in tumor elimination." (PMID 39664386, 2024). "However, it is noteworthy that the PDO cultures did not preserve the tumor immune microenvironment, resulting in negative stainings for CD4 and CD8." (PMID 39204387, 2024). "The other limitations included a lack of genomic and transcriptomic profiling data, a lack of sequential CD8+ and CD4+ T lymphocyte detection in peripheral blood, and a lack of biopsy specimens from metastatic lesions to detect the tumor microenvironment and lymphocyte infiltration." (PMID 38993639, 2024). "Furthermore, stimulating CD4+ T-cells to Th1 cells could enhance CD8+ T-cell activation, promoting anti-tumour activity." (PMID 39348343, 2024).
tumor (continued). "Furthermore, in the grouping based on the B-cell signature gene set, we also observed differences in the number and proportion of CD4+ T cells, CD8+ T cells, and B cells between the two groups, which supports the possibility that there is a gap in anti-tumor immunity with this classifying approach." (PMID 38622125, 2024). "Thus, the inclusion of tumor-unrelated universal CD4 helper antigens (uniHELP) resulted in a clear “helper signature” on vaccine-induced CD8+ T cells, while this signature was marginally detectable in the case of tumor-specific helper neoantigens (neoHELP)." (PMID 39040850, 2024). "Ki67 significantly increased in CD8+ and CD4+ T cells in both the spleen and the tumor site, indicating that CXCL10-Fc also induced these cells in the periphery, but the most significant result is at the tumor site where the relative tumor-specific CD8+ T cells are comparatively high." (PMID 39474427, 2024). "Moreover, the in vivo capacity of tumour-specific B cells to activate tumour-specific CD4+ T cell responses without prior in vitro manipulation has not been assessed." (PMID 38125720, 2024). "Therefore, cryoablation of the primary tumor can not only increase the expression of PD-L1, but also promote the infiltration of CD8+ T cells and increase PD-1 expression on the surface of CD8+ T cells and CD4+ T cells within the secondary tumor." (PMID 39489086, 2024). "When comparing the percentage frequencies of CD45+ cells across EAC samples based on their tissue of origin, we observed that tumor samples generally exhibited an enrichment of T-infiltrating lymphocytes (TILs), specifically CD4+ T cells and NK cells, compared to non-tumoral samples." (PMID 39123475, 2024). "Research has found that a subgroup of CD4+%T cells can produce a cytolytic effect on tumor cells expressing MHC II; Moreover, CD4+%T cells have demonstrated the capability to eradicate tumor cells lacking MHC-II expression through the mobilization of myeloid cells." (PMID 38327747, 2024). "Thus, we divided OSCC patients into different subpopulations based on PLIN3 and B7-H2 expression, and OSCC patients with high PLIN3+B7-H2+ tumor cells had significantly shorter OS and DFS and harbored less absolute count of CD3+CD8+ and CD3+CD4+ T cell infiltration in peripheral blood." (PMID 38554152, 2024). "However, CD4+ T cell depletion did not significantly reduce the tumour-promoting effect of activin A overexpression." (PMID 38472944, 2024). "This suggests that trials might need to target specific subsets of iNKT cells, although recent evidence has shown that relying solely on the expression of CD4 to define the anti-tumor potential of iNKT subsets is not enough." (PMID 39267746, 2024). "In MC38 tumor-bearing mice, oral administration of OMV-Ag-mFC significantly improved the tumor-suppressing microenvironment: tumor-infiltrating CD3+ T cells, CD3+CD8+ T cells, CD3+CD4+ T cells and CD11c+ DCs were increased, and immunosuppressive CD3+CD4+CD25+ Tregs were suppressed considerably." (PMID 38298192, 2024). "Additionally, in agreement with the results obtained with the B16-OVA model, the numbers of tumor-infiltrating CD45+, granzyme B- or IFNγ-producing CD8+ T cells and CD4+ T cells were significantly greater in the TOFA-treated Th9 group than in the untreated Th9 cell group." (PMID 39187636, 2024). "However, the absence of B2m, Jak1 or LMP2 expression on EMT6 tumor cells did not impact the frequency of macrophages, effector CD4+ or CD8+ T cells, or Tregs in the TME." (PMID 38427670, 2024). "Furthermore, 1G11 treatment improves CD3+, CD4 + and CD8 + T cell infiltration in tumor tissue." (PMID 39169307, 2024). "The potential mechanisms of LMR, PLR, and NLR might involve that T lymphocytes such as CD4 and CD8 play a role in tumor suppression mechanisms such as cancer immunosurveillance and cancer immunosedition by inducing tumor cell apoptosis, thereby inhibiting tumor cell proliferation and migration." (PMID 38525418, 2024).
tumor (continued). "Indeed, in 2013, an article illustrated how tumor-derived B16 pericyte upregulated co-stimulatory molecules (CD80 and CD86), the co-inhibitory molecule (PD-L1), and MHC-II, which directly downregulate CD4+ T-cell proliferation and IL-4 and IFN-γ secretion." (PMID 39086395, 2024). "In addition, the estimated exhaustion score of CD8+ Tex cells and Treg score of CD4+ Treg cells were significantly lower in EEC-I group than in the other pathological groups, which may indicate a more active anti-tumor activity." (PMID 39112478, 2024). "ERC1671, combining whole inactivated tumor cells and tumor cell lysates, showed significant effects in rGBM patients, particularly those naive to or resistant to BEV, with an average OS of 328 days and a correlation between peripheral blood CD4+ T lymphocyte counts and survival." (PMID 39877359, 2024). "Additionally, we observed a decrease in the ratio of CD3+/CD8+ TILs in tumor center compared with that in invasive margin, suggesting that intratumoral TILs, TILsTC were comprised of both CD8+ and CD4+ cells, whereas CD4+ cells predominated over CD8+ cells in invasive margin." (PMID 38223758, 2024). "Interestingly, evaluating the association between CD8+ immune phenotypes and tumour stroma, infiltrating PD-L1+ lymphocytes, repeated the trends seen in the IL17A+CD4+-immune phenotype, but the statistical significance was not reached." (PMID 39409156, 2024). "Among them, the distributions of memory B cells, resting CD4 memory T cells, CD4 memory activated T cells, and M1 macrophages were higher, while CD8 T cells, follicular helper T cells, Tregs, activated NK cells, monocytes and M0 macrophages were lower in the “hot” tumor (P < 0.05)." (PMID 39007147, 2024). "Therefore, in subsequent experiments aimed at detecting CD4+ and CD8+ T-cell penetration into the tumor, we treated the animals with just three doses of TGFβ and Cox2 siRNA (1 mg/kg IV BIW) and then sacrificed the mice, excised the livers, and sectioned and stained them." (PMID 38204925, 2024). "However, the anti-tumor efficiency of CD4+T cells did not change among all four passages in the RS cohort of both murine models." (PMID 38891044, 2024). "Furthermore, only immunotherapy, but not chemotherapy, enhanced CD4+ immunity and afforded long-term control of breast cancer growth and resistance to new tumor foci for EMT6 tumors." (PMID 38540350, 2024). "By examining spatial distribution of the T cells in these two models, we observed that both CD8+ and CD4+ T cells are significantly more abundant in the inner parenchyma of Vgll3+ tumors than in Ccne1+ tumors, in which CD8+ T cells are instead especially restricted to the tumor margin." (PMID 38509063, 2024). "Interestingly, the frequency of peripheral CD4+ Treg cells increased from 0.55% ± 0.49 and 0.71% ± 0.54 (in CCA and HCC, respectively) at T0 to 0.99% ± 0.91 and 1.17% ± 0.33 (in CCA and HCC, respectively) at T1, following tumor resection." (PMID 39408071, 2024). "However, CD4+ T cells are not a single cell population; instead, they include T helper cells and regulatory T cells, which demonstrate anti-tumor immune responses and reinforce tumor immune tolerance at the tumor site." (PMID 37405518, 2023). "Especially, DLAT could promote the growth of LIHC cells by targeting autophagy and lead to increased immune invasion of Tregs, thus inhibiting the responses of CD4+ and CD8+T cells and ultimately promoting the occurrence of LIHC by inhibiting anti-tumor immunity." (PMID 36949759, 2023). "In THYM in specific, we found that PEBP1 methylation significantly correlates with infiltration of CD4 T cells, CD4 naïve T cells, CD8 T cells, CD8 naïve T cells, central memory, DC, effector memory, MAIT, macrophages, monocytes, neutrophils, Tfh, Th1, Th2, and nTreg cells in the tumor." (PMID 37894300, 2023).
tumor (continued). "HNSCC patients with higher tumor expression of IL17RB combined with high expression of either the CD4 Tem, memory B cell, or aNK TS had improved prognosis compared to patients with lower expression of IL17RB and high expression of either the CD4 Tem, memory B cell, or aNK TS." (PMID 37111458, 2023). "However, when analyzed as a percentage of total CD3+ cells, MT-Kin-1fl/fl tumors had significantly fewer Treg cells with an increase in percentage of non-Treg CD4+ cells, that was similar to the Met-1 cell-line-derived tumor model." (PMID 36883731, 2023). "Patients with a favorable microbiota profile show higher levels of CD4+ and CD8+ T cells, whereas patients with an unfavorable profile have higher levels of T regulatory cells (Treg) and Myeloid-derived suppressor cells (MDSC), suggesting a role in the development of hotter tumor microenvironment." (PMID 38201531, 2023). "Although attaching an MITD to the immunogenic fragment of KRASG12V did not result in direct recognition of tumor cells by CD4+ T cells, studies have described a bias for endogenous peptides derived from membrane-bound proteins eluted from MHC-II, presumably due to membrane recycling." (PMID 36512410, 2023). "ELISpot results showed that both CD8+ and CD4+ T cells isolated from S100 plus αTim-3-treated mice exhibited a much better ability to initiate the production of IFN-γ than T cells isolated from S100-treated mice or naive mice when incubated with DCs and tumor cell debris." (PMID 37771774, 2023). "Analysis of tumour-infiltrating lymphocytes revealed no changes in the expression of memory-associated markers (CD62L and CD44) or exhaustion-associated markers (TIM3, PD1, LAG3, TOX) in CD4+ or CD8+ cells." (PMID 37605057, 2023). "Moreover, tumor‐derived CD4+CD25+ Tregs activation was reported to inhibit the maturation and function of the DCs, which will abolish antigen‐specific immune responses and promote the tumor progression." (PMID 36226375, 2023). "This study is one of the few reports in which CD4+ and CD8+ cell counts were detected in peripheral blood after many recent studies investigating the relationship between T lymphocyte subsets in tumor microenvironment and tumor development as well as prognosis." (PMID 36983320, 2023). "In addition, the tumor immune infiltration analysis revealed that tumors with low circulating MAPS were infiltrated with more plasma B cells, while tumors with high circulating MAPS were characterized by more CD4+ Th2 cells." (PMID 37950236, 2023). "It has been demonstrated that PD-L1 is expressed in both CD4+ and CD8+ T cells in the tumor microenvironment and that PD-L1+ T cells in the tumor microenvironment inhibit nearby PD-1+ T cells and promote macrophage tumor tolerance, allowing for excessive tumor progression." (PMID 36831655, 2023). "Furthermore, sorafenib treatment increases the number of CD4 + CD25 + FOXP3+ Treg infiltrating HCC and inhibits CXCR4, preventing drug resistance due to the immunosuppressive microenvironment established following sorafenib treatment, suppressing tumor growth." (PMID 36769116, 2023). "Moreover, the spatiotemporal dynamics and the mechanism of action of CD4+ T cells within the tumour tissue have not been fully explained." (PMID 37316667, 2023). "No tumor burden was detected among the CD4-depleted PBMCs and un-engrafted mice." (PMID 37297008, 2023). "Notably, decreases in the ratios of CD4+/CD8+, CD4+FoxP3+/T-bet+CD8+ and CD4+T-bet+/CD4+FoxP3+ TILs were observed during progressive tumour outgrowth, suggesting that the T cell infiltrate in MC38 tumours shifts toward a more pro-inflammatory composition during progressive outgrowth." (PMID 37153625, 2023). "After we had analyzed the somatic copy number alterations (SCNAs) in KIRC, there were significant differences in B cells, CD8+ T cells, CD4+ cells, neutrophils and dendritic cells, which confirmed the prediction that HAMP may regulate the tumor process through immune infiltration." (PMID 36673667, 2023).
tumor (continued). "In antitumor and antichronic viral responses, CD4+ T cells relay help signals through dendritic cells to indirectly regulate CD8+ T cell response, interact with B cells or macrophages to indirectly modulate humoral immunity or macrophage polarization, and inhibit tumor blood vessel formation." (PMID 37829505, 2023). "CD4+ neoantigens are essential in radiation-induced antitumor immune response, as they not only result in enhanced CD8+ T cell activation and cyto-toxicity, but also engage in direct tumor cell killing through interactions with Fas and the death receptor DR5 on tumor cells." (PMID 37377970, 2023). "Moreover, other genes such as TLR4, CD4, COL3A1, and ITGB3 are also of great research value, and whether other genes are also involved in the regulation of tumor bone metastases will be investigated in the later studies." (PMID 37007939, 2023). "Similarly, in the SM1 model, CD4+ but not CD8+ T cell depletion abrogated l-fuc-triggered tumor suppression and increases in total itICs and itIC subpopulations (immunodepletion confirmed by splenic profiling))." (PMID 36690875, 2023). "Therefore, this study assessed the frequency of expanded circulating Th1-, Th17- and Th1/17-like CD3+CD4+ and CD3+CD8+ cells from OGJ cancer patients who underwent surgical tumour resection to determine how major oncologic surgery affects systemic Th1, Treg and Th17 immunity." (PMID 37359545, 2023). "In addition, the metronomic administration of cyclophosphamide seems able to restore immune function by increasing CD4+/CD8+ T cells and depletion of T regulatory cells that may play a role in favoring tumor progression and therapy resistance." (PMID 37568826, 2023). "This would suggest that, for many tumor antigens, central tolerance of CD4+ T cells against thymus-expressed antigens may not necessarily have a negative impact on shaping the anti-tumor B cell or CD8+ T cell repertoire." (PMID 36943460, 2023). "In contrast to most in vitro studies involving PBLs, we did not address the anti-tumor functions of NK and T cells individually but evaluated the interplay between CD4+ T cells, CD8+ T cells and NK cells on immune cell activation and tumor lysis upon delivery of IL-15/IL-15Rα and K2-Fc." (PMID 37923822, 2023). "Moreover we found that NK cells or CD8+ T cells, but not CD4+ T cells, were required for tumor cell killing." (PMID 37923822, 2023). "Our spatial analysis showed that there were significant differences between the ER and LR groups and between the DM and non-DM groups in the density of CD3+ or CD4+ immune cells in all tumor regions, including the TC, IM, combined tumor region, and all three hotspots." (PMID 37090736, 2023). "Tumor-specific upregulation of cytokines produced by Th17 CD4+ cells, such as IL-17A and IL-22, has been observed in human CRC, and studies in mouse models of spontaneous intestinal tumorigenesis have demonstrated the importance of these cytokines in tumor progression." (PMID 38096329, 2023). "CD4+ T cells may also provide local help for CD8+ T cells within tumors by secreting cytokines such as IL-2 and IFN-γ, supporting CD8+ T cell survival and recruitment to the tumor." (PMID 36512410, 2023). "CD4+, CD8+ T cells, macrophages, and DCs expressing the receptors of these chemokines were recruited into ESCC, where these cells were regulated by complex signaling from the regional tumor microenvironment and presented diverse capabilities participating in pro- or antitumor immune response." (PMID 37275884, 2023). "Moreover, TCRαβ+CD4−CD8−NK1.1− innate αβ T cells (iαβT) promote M1-like proinflammatory reprogramming of macrophages in a CCR5-dependent manner with enhanced antigen presentation and T-cell chemoattraction, this way improving CD4+ and CD8+ cytotoxic T-cell toward the tumor." (PMID 38274812, 2023).